FTO (FTO alpha-ketoglutarate dependent dioxygenase)
Diseases named in the same sentence as FTO in open-access papers (continued):
Sharing a sentence is not in itself a finding about the gene and the disease.
cancer (continued). "Moreover, FTO has been demonstrated to play a role in cancer, operating as an oncoprotein in leukemia and participating in critical biological processes." (PMID 38384328, 2024). "For instance, it was suggested that the exact role of FTO remains controversial in human cancers." (PMID 38075202, 2024). "FTO is commonly dysregulated and exerts significant effects on different categories of cancer." (PMID 37299548, 2023). "On the other hand, FTO, a m6A demethylase, was inversely correlated with TSs in most cancer types." (PMID 36239411, 2023). "As an m6A demethylase, FTO could regulate multiple functions in cancers, such as cell cycle, apoptosis, proliferation, migration, invasion, stem cell self-renewal and so on." (PMID 37598390, 2023). "FTO plays critical roles in cancer stem cell maintenance and immune evasion." (PMID 37671941, 2023). "However, the data on m6A and FTO in drug resistance is still limited and inconsistent, and more studies are needed to elucidate their role in different types of cancers and drugs." (PMID 37605223, 2023). "Furthermore, FTO, the key “eraser” of m6A, has been confirmed to be an essential regulator in several cancers." (PMID 37840133, 2023). "Two studies investigated the co-expression of ALKBH5 and FTO in cancers." (PMID 36582218, 2023). "Both ALKBH5 and FTO can regulate the cancer epigenome through demethylation of mRNA m6A, leading to changes in the ability of cells to survive, proliferate, invade, and metastasize as alterations in drug sensitivity, cancer stem cell status, and cancer immunity." (PMID 37007161, 2023). "Meanwhile, FTO has the ability to stimulate cancer cell proliferation, enhance the self-renewal of cancer stem cells, and alter the immune and metabolic characteristics of cancer cells by eliminating the m6A modification from its target mRNAs and regulating their stability." (PMID 37299548, 2023). "FTO inhibitors have been reported to exhibit both anti-obesity and anti-cancer effects in vivo." (PMID 37471425, 2023). "In addition to FTO, other m6A enzymes are also involved in cancer drug resistance via regulating metabolism." (PMID 37055798, 2023). "Notably, FTO as a therapeutic target has been reported in many types of cancers and experimental models." (PMID 37175660, 2023). "Therefore, an improved methodology is needed to fully explore the exact context of the role of ALKBH5 and FTO in cancer, especially for those cancers where the role of ALKBH5 and FTO is highly controversial." (PMID 37007161, 2023). "As the first identified RNA m6A demethylase, FTO is the most studied and found to be frequently dysregulated in its expression, localization, post‐translational modification and functions in various types of cancers." (PMID 36260366, 2023). "It has been shown that FTO exhibits oncogenic effects in BCa by regulating the expression of cell cycle protein-dependent kinase (CDK6), which is closely related to the cell cycle, and mechanistically promotes cancer cell proliferation and invasion in BCa through the FTO/miR-576/CDK6 pathway." (PMID 38117350, 2023). "Functional assays indicated an anti-cancer role of FTO and ALKBH5 in CRC." (PMID 37580808, 2023). "Therefore, FTO’s impact on cancer is primarily determined by its functional targets in a specific cancer type or cellular context." (PMID 37919739, 2023). "Both miR-155 and FTO are dysregulated in cancers, and the interplays between m6Am in miR-155 targets and FTO could be a possible regulatory mechanism exploited in cancers." (PMID 35886072, 2022). "Most importantly, FTO-dependent m6A demethylation could regulate glycolytic enzymes in opposite directions in a cancer-type-specific manner." (PMID 36289851, 2022). "Additionally, FTO loss led to the reversal of EMT traits, impaired tumorsphere formation, and reduced the expression of cancer stem cells (CSC) markers." (PMID 36497402, 2022). "FTO has been confirmed as an oncogene in cancers including AML, MM, OSCC, and NSCLC." (PMID 35864970, 2022).
cancer (continued). "FTO was highly expressed in half of human cancers, including HNSCC." (PMID 35395767, 2022). "Furthermore, FTO-mediated RNA demethylation was also involved in S-adenosylmethionine decarboxylase proenzyme (AMD1)-induced cancer stemness in HCC." (PMID 35859892, 2022). "In addition, two compounds known as CS1 and CS2 were shown to bind tightly to the FTO protein and block its catalysis, thus exhibiting potent antitumor effects in several types of cancer." (PMID 36389416, 2022). "The pro-proliferative role of the m6A eraser FTO is well-studied within the context of cancer." (PMID 35350378, 2022). "Similarly, mRNA expression of FTO was frequently increased in cancer tissues compared with matched normal tissues." (PMID 35311620, 2022). "Similarly, knockdown of FTO in TA-MSCs decreased their pro-tumorigenic effect while overexpression of FTO rescued the decreased function of cancer cells induced by MIF knockdown in TA-MSCs." (PMID 35794625, 2022). "Furthermore, FTO promotes cancer progression by regulating the expression of MZF1, and knockdown of FTO inhibits cell proliferation and invasion." (PMID 38089085, 2022). "As the main M6A eraser, FTO has been widely accepted to have a significant role in cancers." (PMID 35530301, 2022). "FTO, as an m6A mRNA demethylase, is involved in various cancers." (PMID 35961973, 2022). "In lung cancer, proliferation of cancer cells could be promoted by FTO-mediated upregulation of KRAS or MZF1 signaling." (PMID 35804965, 2022). "Additionally, using a series of gain- and loss-of-function studies, we unambiguously showed the essential requirement of FTO overexpression in conferring enhanced proliferative advantage to the cancer cells against the normal cells." (PMID 36497402, 2022). "The role of FTO in cancer has recently garnered increasing attention." (PMID 35311150, 2022). "As proof of concept, FTO inhibitors were demonstrated to possess anticancer properties both in vitro and in mice experiments, by inhibiting growth/survival and by sensitizing cancer cells to chemotherapeutic drugs." (PMID 36551531, 2022). "Regarding immunotherapy against cancer cells, FTO was identified as an essential regulator of glycolytic metabolism that tumors could use to escape immune surveillance." (PMID 35186927, 2022). "In addition, considering the importance of m6A modification in human cancers, it is possible to explore new strategies for the diagnosis and treatment of OS by targeting FTO with selective inhibitors." (PMID 35311620, 2022). "FTO, as the first identified m6A demethylase, becomes a research hotspot in cancer." (PMID 37529797, 2022). "Given the functional significance of FTO in cancer, several FTO inhibitors have been developed." (PMID 36009465, 2022). "Thus, our findings suggest the PIKE-A/STAT3/FTO/SDHA axis as promising anti-cancer treatment targets." (PMID 36232604, 2022). "It has been shown that amino acid transporters can be regulated by m6A modification, as the main glutamine transporter SLC1A5 in cancer cells can be regulated by the m6A modified demethylase FTO and SLC7A11 is promoted to decay by preferentially bound to YTHDC2." (PMID 35054897, 2022). "As a demethylase, FTO has been reported to play a crucial role in various cancers." (PMID 35397614, 2022). "Furthermore, a recent study in AML has demonstrated FTO inhibition’s relevance in curbing the self-renewal of cancer stem cells and immune evasion." (PMID 36497402, 2022). "In cancer cells, FTO is also important for the expression of lipogenic enzymes." (PMID 36289851, 2022). "Therefore, FTO represented a modern therapeutic potential to target cancer therapy, and more clinical studies were required to confirm the long-term side effects of these inhibitors." (PMID 36517820, 2022). "In peripheral tissues, FTO is related to energy metabolism and cancer progression." (PMID 36163017, 2022).
cancer (continued). "Moreover, FTO influences the progression of cancer by regulating multiple signaling pathways, such as FTO-PGC-1 α signaling axis, mediating PKM2 demethylation, impairing the translation efficiency of E2F1 and Myc." (PMID 33692753, 2021). "Although it remains unknown how FTO participates in CRC tumorigenesis, FTO inhibitors have been widely explored as anticancer drugs in other types of cancer." (PMID 33456561, 2021). "In addition, the relationship between FTO expression and pan-cancer survival was analyzed based on TCGA database data." (PMID 35299934, 2021). "Recently, FTO has been identified as m6A and m6Am demethylase of mRNA and small nuclear RNA (snRNA) in the cell nucleus and cytoplasm 73-75, which performs m6A-related function in many types of cancer 76-79." (PMID 33456561, 2021). "In osteosarcoma, low expression of FTO and METTL14 as well as high expression of METTL3 and YTHDF3 were associated with cancer metastasis and could be used as biomarkers to predict poor prognosis." (PMID 34345203, 2021). "Additionally, the depletion of FTO proved beneficial in cancer models, as it led to increased RNA decay through the m6A reader YTHDF2." (PMID 33807762, 2021). "Clarifying the mystery of crosstalk between FTO and other epigenetic members might guide to improve treatment efficiency of cancers." (PMID 33754077, 2021). "Besides, recent studies have shown that depletion or inhibition of FTO suppresses the expression of immune checkpoint genes and attenuates the self-renewal ability of cancer stem cells, thus overcoming their immune escape." (PMID 35004679, 2021). "Therefore, the development of selective and effective inhibitors targeting FTO will have the potential to treat cancer, particularly in combination with other therapies to treat cancers that are resistant to currently available therapies." (PMID 34124065, 2021). "FTO has since been widely reported to function as an oncogene in a variety of cancer types." (PMID 34544449, 2021). "Evidences have shown that FTO involves in the process of malignant tumors." (PMID 34281544, 2021). "In addition, there are other FTO inhibitors, such as Meclofenamic acid (MA) was applied to cancer treatments." (PMID 34345203, 2021). "In addition, a significant antitumor drug effect was also found in drug-treated cancer cells combined with FTO inhibitors." (PMID 34745970, 2021). "This implicates its specific role in cancer cells and adds to the interest in FTO regulation." (PMID 33925955, 2021). "Our findings supported that FTO may act as a potential GC biomarker and shed light on future cancer." (PMID 34277426, 2021). "On the other hand, recent studies have reported that there is a strong association between FTO single nucleotide polymorphisms (SNPs) such as rs9939609 with the increased risk of some types of BC, implying a possible mediatory role of FTO in the pathogenesis of cancers." (PMID 33634577, 2021). "However, FTO is a double-edged sword in regulating the chemoradiotherapy sensitivity of cancer cells." (PMID 34076564, 2021). "The answers to these questions may contribute to the development of novel methods to restore the dysregulation of FTO in human cancers." (PMID 34378866, 2021). "In addition, some biotech or pharmaceutic companies get down to developing high-efficiency small-molecule inhibitors, targeting the m6A regulators, in particular molecules like METTL3 and FTO that vary significantly in many cancers." (PMID 35004679, 2021). "Besides of energy disorder, FTO participates in the regulation of prognosis of cancer through several other ways." (PMID 34149936, 2021). "In addition to these conflicting reports about the role FTO plays in different cancers, the function of FTO in CRC is unclear so far." (PMID 34218271, 2021).
cancer (continued). "Compared with the control group, expression levels of HNRNPC, YTHDF1, KIAA1429, RBM15, YTHDF2, and METTL3 in cancer group were significantly up-regulated (P < 0.05), while expression levels of FTO, ZC3H13, METTL14, YTHDC1, and WTAP in cancer group were significantly down-regulated (P < 0.05)." (PMID 33193582, 2020). "FTO is highly expressed in many cancer tissues, which plays the role of an oncogene in an m6A-dependent way and participates in the regulation of the malignant phenotype of cancer cells." (PMID 33304380, 2020). "Although there is no direct evidence that FTO SNPs are associated with cancer by affecting the expression of adjacent genes, we cannot rule it out as a possibility." (PMID 33304380, 2020). "However, it seems that ALKBH5 and FTO can have an opposite role in other cancer types, suggesting a complex regulation system." (PMID 33375621, 2020). "It has been suggested that FTO may directly regulate food intake, fat development, energy metabolism, cell proliferation, and cancer development." (PMID 32747736, 2020). "EGCG has an anti-cancer effect, but it needs to be further clarified if it through inhibiting FTO." (PMID 33304380, 2020). "The FTO expression was markedly declined in cancer counterpart and lost in the later stage." (PMID 32513173, 2020). "Previous studies reported that RNA m6A methylation could affect various biological processes and signaling pathways, such as self-renewal and tumorigenesis of cancer stem cells, RNA metabolism, the FTO/m6A/MYC/CEBPA signaling, and the IL-7/STAT5/SOCS pathways." (PMID 32419773, 2020). "Recent studies demonstrated that FTO plays an oncogenic role in cancers." (PMID 31143705, 2019). "Further research on the exact mechanism of the influence of FTO gene on the growth and proliferation of cancer cells may clarify the importance of this issue and the possibility of therapeutic use of dietary components in cancer." (PMID 31447604, 2019). "A number of studies have attested to the tumorigenic role of FTO in various sorts of cancers." (PMID 31921664, 2019). "Collectively, these findings prove that FTO is involved in various cancer development." (PMID 31519943, 2019). "However, due to the tumorigenic role of FTO in various cancers, scientist have developed several FTO inhibitors as promising tools in antileukemia and antiglioblastoma therapies." (PMID 31921664, 2019). "In low grade glioma and subsets of IDH-mutant AML cases in which the presence of 2HG leads to a more benign outcome, we suggest that 2HG contributes to cancer initiation via inhibiting TET2, but suppresses cancer progression/proliferation via inhibiting FTO/MYC signaling." (PMID 29686311, 2018). "This review focuses on the functions of FTO in both adipogenesis and tumorigenesis and on the underlying m6A-dependent mechanisms, along with a brief discussion of recent advance in the development of FTO inhibitors and their therapeutic potential to treat cancers." (PMID 30105001, 2018). "FTO has also been reported to affect the response of cancer cells to drug treatment." (PMID 30105001, 2018). "The comparison between overexpression of wild-type FTO and mutated FTO (H231A and D233A) in MLL-rearranged AML cells showed that only overexpression of wild-type FTO could promote cancer cell growth." (PMID 29374143, 2018). "In conclusion, our updated meta-analysis supported that FTO SNP was associated with some types of cancer, which was mediated by BMI or independent of BMI." (PMID 28881622, 2017). "This study overall does not support that the FTO variant is associated with cancer risk independently of the adiposity." (PMID 28881622, 2017). "As FTO SNP rs9939609 was strongly associated with BMI, it is not surprising that this variant was associated with some types of cancer but not with other types of cancer." (PMID 28881622, 2017).
cancer (continued). "Additionally, FTO protein may act as an oncogene regulating the phenotypic malignancies of cancer in an m6A-dependent manner and may contribute to therapy resistance." (PMID 40722726, 2025). "Moreover, it was also found that FTO targeting suppression could inhibit cancer stem cell maintenance and promote their immune evasion." (PMID 41255573, 2025). "Additionally, FTO may enhance cancer cell proliferation via the PI3K/AKT pathway, making its modulation through LCKD particularly relevant in cancer-prone individuals; however, the outcome may depend on the genotype." (PMID 40626223, 2025). "Therefore, understanding the binding sites of FTO may offer insights into reducing cancer incidence to a certain extent." (PMID 40646842, 2025). "Thus, targeting the upstream SRSF6/FTO feedback loop might be an alternative strategy to overcome cellular ferroptosis resistance in cancer therapy." (PMID 40712780, 2025). "Thus, FTO has been reported to be an eraser that functions in a cancer‐promoting manner." (PMID 40448344, 2025). "Interestingly, another study reported that FTO could facilitate cancer cell escaping from immune surveillance via enhancing glucose metabolism." (PMID 41255573, 2025). "Considering that FTO is an RNA demethylase frequently upregulated in many tumors and represents a risk factor for overall survival, K. pinnata emerges as a potential therapeutic option for aggressive cancers, such as hormone receptor-negative tumors." (PMID 40572597, 2025). "The functions of FTO in the development of cancers remain unclear." (PMID 39897037, 2025). "However, whether ALKBH5 or FTO are required for ATF4 mRNA translation in chemotherapeutic-treated cancer cells to promote resistance is still unknown." (PMID 39199320, 2024). "Thus, we want to explore the possibility by targeting FTO to kill the cancer." (PMID 38600610, 2024). "Additionally, FTO expression is suppressed in ovarian tumors and cancer stem cells (CSCs)." (PMID 39192357, 2024). "The FTO-m6A axis may serve as a new potential therapeutic target for human cancers." (PMID 37626050, 2023). "Therefore, understanding the molecular mechanisms of m6A and FTO in drug resistance may provide new insights for overcoming therapy resistance and improving cancer treatment outcomes." (PMID 37605223, 2023). "Besides of that, the combination of FTO inhibitors and conventional chemotherapy may be a more effective strategy for cancer therapy." (PMID 37402730, 2023). "In addition, FTO is critical to the adaptive response of cancer cells to glutamine deprivation." (PMID 36289851, 2022). "However, FTO also exerts inhibitory effects on certain types of cancer." (PMID 35804965, 2022). "In addition, the FTO gene–nutrition interaction as an underlying mechanism of cancer has not been well established." (PMID 36403211, 2022). "Moreover, Dac51 (a small molecule) can block FTO-mediated immune evasion and control immunity, suggesting that RNA epitranscriptome could promise a new strategy for immunotherapy against cancer cells." (PMID 35186927, 2022). "In addition, PD1/PD-L1 checkpoint blockade is regulated by YTHDF1 (m6A reader) and FTO (eraser), and m6A modulators may be potential anti-cancer immunotherapy targets." (PMID 35281840, 2022). "Here, we determined whether FTO depletion altered the mitochondrial dynamics of cancer cells." (PMID 35064107, 2022). "Given the recent confirmation that vitamin C binds directly to FTO and the diverse roles of m6A in the regulation of gene expression in cancer the role of vitamin C in m6A demethylation and the implication on genomic stability and cancer therapy requires further investigation." (PMID 34017357, 2021). "Evidences have found that ALKBH5 and FTO could promote cancer tumorigenesis." (PMID 32884942, 2020). "However, ALKBH5 and FTO have been reported as a tumor suppressor by inhibiting cancer progression." (PMID 32884942, 2020). "FTO may also have an impact on the therapeutic response of cancer." (PMID 33304380, 2020).